ABCB5 (ATP binding cassette subfamily B member 5)
Diseases named in the same sentence as ABCB5 in open-access papers (continued):
Sharing a sentence is not in itself a finding about the gene and the disease.
melanoma (continued). "Significant differences between levels of water-soluble metabolites in ABCB5-WT and ABCB5-KD G3361 melanoma cells based on 1H NMR spectroscopy of cell extracts." (PMID 27560924, 2016). "Our results provide initial evidence that ABCB5 is not only a marker of murine melanoma CSCs, but also perform functional roles in murine melanoma growth and multidrug resistance." (PMID 26910836, 2016). "ABCB5-positive melanoma cells inoculated into immunodeficient mice showed greater tumorigenic capacity than ABCB5-negative cells." (PMID 26666373, 2015). "ABCB5 expression in tumor cells was seen to correlate with clinical melanoma progression and a subpopulation of human melanoma cells was observed to coexpress ABCB1, ABCB5, and ABCC2 in addition to stem cell markers." (PMID 26649310, 2015). "ABCB5-positive melanoma cells inoculated into immunodeficient mice showed greater tumorigenic capacity than the ABCB5-negative melanoma cells." (PMID 26666373, 2015). "The present study revealed that it is not highly cytotoxic but markedly reduced the frequency of slow-cycling melanoma cells and ABCB5-positive melanoma cells." (PMID 24595456, 2014). "It was demonstrated that anti-ABCB5 antibody or siRNA gene silencing reversed melanoma resistance to anticancer drugs." (PMID 24595456, 2014). "Nevertheless, our results position bryostatin 1, siomycin A, pentoxifylline, illudin M and michellamine B as drugs against melanoma stem-like cells and potentially resistance-reversing agents capable of reducing ABCB5 expression." (PMID 24595456, 2014). "CTCs were captured by targeting the melanoma associated markers MCSP and MCAM as well as the melanoma stem cell markers ABCB5 and CD271." (PMID 24915896, 2014). "Treatment of melanoma cells with PLX4032 or cytotoxic anti-cancer drugs had been shown to result in the selection of ABCB5-expressing cells." (PMID 25300205, 2014). "In the present study, the reduction of cells with clonogenic capacity, ABCB5-positive and slow-cycling cells indicates that siomycin A at 1 μM is more effective against melanoma stem-like cells than against fast-cycling cells." (PMID 24595456, 2014). "Those compounds substantially decreased the frequency of ABCB5-positive melanoma cells and removed the slow-cycling label-retaining cells at concentrations that did not trigger apoptosis." (PMID 24595456, 2014). "It has been reported that CD133+ and ABCB5+ subpopulations are colocalized in melanomas in perivascular niches that contain vascular endothelial (VE)− cadherin+ melanoma cells, which have the ability to form VM." (PMID 24179490, 2013). "ABCB5, a known chemoresistance mediator in melanoma, was expressed in only a minority of tumor cells (1.6–20.4%) and only ABCB5+ cells were capable of establishing primary grafts and serially transplanting disease in NOD/SCID mice." (PMID 24294611, 2013). "Inhibition of ABCB5 dramatically improved intracellular drug accumulation and reduced the resistance of melanoma cells to doxorubicin." (PMID 24416617, 2013). "ABCB5, presenting an increased expression during the malignant transformation, has been involved in the resistance of melanoma cells to doxorubicin." (PMID 24416617, 2013). "We confirmed that FKBP51 knockdown resulted in ABCB5 decrease in several melanoma cell lines, using a different siRNA." (PMID 23559012, 2013). "Consistent high levels of CD133 and ABCB5 marker expression were observed in 100% tissues from patients with primary melanoma that successively progressed to lymph node metastasis (100%) and distant metastasis (83% and 66%, respectively)." (PMID 22922842, 2012). "Of note, the WM-115 cell line derived from a primary melanoma tumor expresses six times less ABCB5 mRNA than the WM-266-4 cell line which originates from a metastasis of the same patient." (PMID 22675422, 2012). "This variability is in agreement with previous analyses of a panel of melanoma cell lines and was confirmed when measuring the ABCB5 mRNA content by Q-PCR." (PMID 22675422, 2012).
melanoma (continued). "Taken together, our results suggest that anti-melanoma chemotherapy participates to the chemoresistance acquisition that leads to clinical relapse, by selecting tumor cell subpopulations such as ABCB5-expressing cells." (PMID 22675422, 2012). "We analyzed the expression of ABCB5 in human melanoma metastatic samples obtained from unmatched patients, before and after treatment." (PMID 22675422, 2012). "The preferential ABCB5 expression in melanocytes and melanomas pointed to a potential link between ABCB5 and the melanosomal compartment in which melanin is synthetized and stored." (PMID 22675422, 2012). "Among the downregulated genes were TYRP1 (tyrosinase-related protein 1) and ABCB5 (ATP-binding cassette, sub-family B, member 5), both of which are related to melanoma progression and initiation." (PMID 23056502, 2012). "Because the expression of different ABC transporters has been observed in melanoma, we evaluated their potential implication in the ABCB5+ cells survival upon dacarbazine as well as other chemotherapeutic agents." (PMID 22675422, 2012). "A second helicase, recently shown to be expressed in a subpopulation of melanoma cells, referred to as ABCB5+ malignant melanoma-initiating cells, is HAGE (alias Cancer/testis antigen 13 (CT13); DDX43)." (PMID 23116066, 2012). "Here, we demonstrated that ABCB5+ cells display a survival advantage over ABCB5− cells upon anti-melanoma treatment." (PMID 22675422, 2012). "Since ABCB5 expression has been shown to vary according to the melanoma stage, we restricted our study to skin metastases from untreated patients and from patients who relapsed after a first chemotherapy episode." (PMID 22675422, 2012). "Here, we re-examined ABCB5 cell-surface expression by flow cytometry in five melanoma cell lines using a different anti-ABCB5 antibody." (PMID 22675422, 2012). "ATP-binding cassette sub-family B member 5 (ABCB5) and CD271 have been shown to be associated with a melanoma initiating cell phenotype." (PMID 22978632, 2012). "Firstly detected in tissues derived from the neuroectodermal lineage including melanocyte progenitors, melanoma cell lines and patient specimens, ABCB5 expression was also found in other tissues but is restricted to a subpopulation of cells." (PMID 22675422, 2012). "We captured CMCs by targeting the melanoma associated markers MCSP and MCAM as well as the melanoma stem cell markers ABCB5 and CD271, both individually and in combination, by immunomagnetic enrichment." (PMID 22978632, 2012). "We investigated the effect of an anti-melanoma chemotherapeutic treatment on the ABCB5-expressing cell subpopulation in vivo." (PMID 22675422, 2012). "This is of particular importance in understanding the relapses observed after anti-melanoma treatments and reinforces the interest of ABCB5 and ABCB5-expressing cells as potential therapeutic targets in melanoma." (PMID 22675422, 2012). "As a member of the ABC transporters family, ABCB5 was suggested to participate to the chemoresistant phenotype of melanoma cells." (PMID 22675422, 2012). "In melanoma, ABCB5-expressing cells are endowed with self-renewal, differentiation and tumorigenicity abilities." (PMID 22675422, 2012). "ABCB5 expression was initially detected in a subpopulation of a melanoma cell line (G3361), as well as in melanoma samples obtained from patients." (PMID 22675422, 2012). "The polarization towards regulatory T cells by ABCB5+ melanoma initiating cells has been attributed in part to the expression of co-stimulatory CD86 by these cells." (PMID 21526207, 2011). "Accordingly, high expression of the drug transporter and chemoresistance mediator ABCB5 has been correlated with melanoma progression, and specific targeting of the ABCB5+ population with a monoclonal antibody significantly inhibited tumor growth in patients." (PMID 24212957, 2011).
melanoma (continued). "There is evidence in the literature that shows inhibition of ABCB5 either at the protein or mRNA level can inhibit doxorubicin transport and also sensitize melanoma and liver cancer stem cells to the drug." (PMID 21298007, 2011). "A number of distinct forms of ABCB5 have been shown to be expressed in various tissue types, including, but not limited to, melanocytes, melanoma cells, testis, mammary tissue, and retinal pigmented epithelium." (PMID 21298007, 2011). "ABCB5 has also been found to be expressed at the transcriptional level in a number of cancer subtypes, including malignant melanoma, breast cancer, colorectal cancer and hepatocellular carcinoma, and also has been linked to leukemia." (PMID 21298007, 2011). "A recent study attributed a preferential capacity to modulate the immune response to melanoma initiating cells expressing ABCB5 and MHC class II molecules." (PMID 21526207, 2011). "The authors showed that ABCB5+MHC class II+ cells displayed higher capacity than ABCB5- MHC class II-negative melanoma cells to inhibit IL-2-dependent T-cell activation and support the induction of CD4+CD25+FoxP3+ regulatory T cells." (PMID 21526207, 2011). "ABCB5 is a marker of human melanoma CSCs, and CSCs with ABCB5 have a strong ability to generate tumors in xenotransplantation assays." (PMID 20950440, 2010). "A previous report has shown that human melanomas also contain CSCs, and these tumor derived CSCs express ABCB5." (PMID 20950440, 2010). "In particular, in regards to melanoma, ABCB5 is overexpressed in melanoma and ABCG2 is expressed by a sub-fraction of CD133-positive melanoma cell population." (PMID 21203549, 2010). "In serial xenotransplantation experiments ABCB5+ melanoma cells were more tumorigenic than ABCB5- cells." (PMID 20459772, 2010). "We examined the expression of CD133, CD44, CD24, and ABCB5 during tumorigenesis of B16 melanoma cells transfected with empty or GDF3-expressing vectors." (PMID 20950440, 2010). "Furthermore, we determined if VPA-induced ABCB5 influences the acquisition of the MDR phenotype using DOX as a known substrate of the ABCB5 protein, which confers chemotherapy resistance in melanoma." (PMID 41020871, 2025). "At the transcriptional level, ABCB5 is expressed in malignant melanoma, breast cancer, colorectal cancer, hepatocellular cancer, and leukemia, and it is considered a marker of cancer stem cells, particularly in melanoma and colorectal cancer." (PMID 41020871, 2025). "As a transmembrane P-glycoprotein regulating the efflux of substances as an MDR transporter, ABCB5 regulates the efflux of various substances, potentially enabling skin-derived ABCB5+ MSCs to interfere with drug resistance in cancers such as melanoma, thereby enhancing the efficacy of chemotherapy." (PMID 39941329, 2025). "Thus, we investigated the EMT-related molecular signature of these hybrid stem mesenchymal CMCs (CD45−CD146+ABCB5+) as potential biomarkers of melanoma progression and/or aggressiveness." (PMID 40332096, 2025). "ABCB5 mediates melanoma therapy resistance through the efflux of chemotherapeutic drugs." (PMID 40867277, 2025). "Melanoma CSCs can be identified by surface markers, such as cluster of differentiation (CD) 133, CD20, CD271, aldehyde dehydrogenases (ALDHs), and ATP-binding cassette sub-family B member 5 (ABCB5), which are associated with their tumorigenic potential and resistance to treatment." (PMID 40867277, 2025). "In BRAF inhibitor-resistant melanoma cell lines, ABCB5 is overexpressed, indicating its role in resistance mechanisms, although it may not be a primary targetable contributor." (PMID 40867277, 2025). "Higher ABCB5 level increase the chemoresistance to cisplatin in malignant melanoma, suggesting that ABCB5 may be a new target to enhance the drug efficacy of cisplatin." (PMID 40746888, 2025).
melanoma (continued). "ABCB5 is a marker of melanoma aggressiveness, multidrug resistance, and stemness, and has been reported to induce unique modifications of metabolism in melanoma-initiating cell lines." (PMID 40558548, 2025). "Additionally, ABCB5+ melanoma cells have been reported to exhibit markedly reduced or absent expression of MHC class I molecules, allowing these cells to escape recognition by CD8+ T cells and thereby impairing the anti-tumor immune response." (PMID 39611156, 2024). "ABCB5 has been proposed as a reliable marker of melanoma aggressiveness, multidrug resistance and stemness; it has also been found to induce peculiar modifications of the cellular metabolism in melanoma-initiating cell lines." (PMID 39199632, 2024). "In addition, ABCB5 was shown to mediate resistance to caffeic acid phenethyl ester, a bioactive molecule with antitumor activity, in melanoma." (PMID 39267923, 2024). "Interestingly, by flow cytometry using the 3C2-1D12 antibody, most of the purified CD133+ melanoma tumor cells were shown to express ABCB5, and the purified CD133+/ABCB5+ cells were able to regenerate a heterogeneous tumor in in vitro culture." (PMID 39267923, 2024). "ABCB5-knockout melanoma cells have lower succinic acid levels than wild-type cells." (PMID 39330487, 2024). "Similarly, ABCB5 mRNA was increased in a human melanoma side population selected by Hoechst 33342 dye exclusion." (PMID 39267923, 2024). "Similarly, patients with melanoma treated with dacarbazine had increased ABCB5 mRNA expression, and treatment with dacarbazine in vitro resulted in the selection of ABCB5-expressing cells." (PMID 39267923, 2024). "Similarly, ABCB5 mRNA was six times less expressed in WM-115, derived from a primary melanoma tumor, compared to WM-266-4, derived from metastasis from the same patient." (PMID 39267923, 2024). "ABCB5 is thought to also mediate chemoresistance of doxorubicin in malignant melanoma." (PMID 38179408, 2023). "In addition, cancer progression has been associated with the overexpression of some other ABC transporters, as in the case of melanoma, where a clinical correlation with ABCB5 expression was found." (PMID 38004589, 2023). "Moreover, CD133+ melanoma CSCs expressed higher levels of ABCB5 compared to CD113− cells and are resistant to the antiapoptotic activity of the natural compound caffeic acid phenethyl ester." (PMID 36498571, 2022). "Progression of melanoma is clinically correlated with ABCB5 expression." (PMID 35505363, 2022). "In addition, it has been reported that CD133+ and ABCB5+ subpopulations colocalized in melanomas in perivascular niches that contain vascular endothelial (VE)- cadherin+ melanoma cells, which can form VM." (PMID 36145658, 2022). "However, in a more recent report, ABCB5 was found to enhance tumorigenic ability and promote melanoma metastasis by activating the NF-κB cascade." (PMID 35048028, 2021). "In addition, in previously published studies, subconjunctival injection of 0.4 × 106 conjunctival melanoma cells (i.e., a dose similar to that of the ABCB5+ LSCs in the present study) to NSG mice resulted in ocular tumor development in 100% of the animals." (PMID 33741066, 2021). "Interestingly, these authors have revealed that Abcb5 transcript level is relatively decreased in melanoma in comparison to normal pigment cells." (PMID 33804686, 2021). "Human tumorigenic melanoma reveals that few melanoma cells express ABCB5." (PMID 32548126, 2020). "ABCB5 is commonly overexpressed on circulating melanoma tumor cells." (PMID 33114317, 2020). "In addition, the well-characterized melanoma SC marker ABCB5 was assessed by flow cytometry in spheres and adherent cells." (PMID 32423311, 2020). "Several findings documented that tumorigenic heterogeneity within the melanoma VGP is the definition of a subpopulation of human melanoma cells that express the multidrug resistance transporter known as adenosine triphosphate–binding cassette subfamily B, ABCB5." (PMID 32548126, 2020).
melanoma (continued). "ABCB5 mediates doxorubicin chemoresistance in human malignant melanoma, and is preferentially expressed on chemoresistant CD133-expressing tumor cells which indicates that this ABC transporter may be a marker of more primitive melanoma cells." (PMID 33114317, 2020). "It has been also shown that ABCB5 (ATP-binding cassette, sub-family B, member 5) contributes to WNT-dependent expression of CXCL8 (C-X-C motif chemokine ligand 8) encoding interleukin-8 to support a slow-cycling and chemoresistant phenotype of melanoma cells." (PMID 31659567, 2020). "However, the observed effect of docetaxel on ABCB5 signals in external melanoma cells is compatible with either, an up-regulation of ABCB5 in weakly expressing cells or selection of strongly expressing cells." (PMID 31035967, 2019). "Considering the multidrug resistance capabilities of ABCB5 for doxorubicin and temozolomide in melanoma cells, we wondered whether there would be a correlation between ABCB5 expression and melanoma cell survival to drug treatment also in the tri-culture model." (PMID 31035967, 2019). "Since ABCB5 is a common marker in CTCs but expressed only in rare cell subpopulations in matched melanoma tumour tissues, it is possible that rare tumour subpopulations, through ABCB5 expression, might acquire invasive capabilities via EMT activation." (PMID 30769764, 2019). "The ABCB5 gene, although not previously associated with sarcoma, has been previously associated with clinical drug resistance and recurrence in malignant melanomas and leukaemias." (PMID 31053105, 2019). "This study confirms the phenotypic and molecular heterogeneity observed in melanoma CTCs and highlights genes and cellular pathways that may be associated with the biology of MCSP or ABCB5 CTC subtypes." (PMID 30769764, 2019). "Mostly melanoma cells as well as keratinocytes showed ABCB5 immunoreactivity." (PMID 31035967, 2019). "Moreover, melanoma tumour cells expressing ABCB5 have been found to escape chemotherapy and MAPK inhibition, possibly as a result of its drug-efflux function." (PMID 30769764, 2019). "In addition, the changes in ABCB5 differed between the early passages and the late passages of melanoma cells in response to BRAF treatment." (PMID 29929490, 2018). "Subsequently, ABCB5 was identified as a potential predictor of active recurrence/progression events, with its expression in blood correlating with disease recurrence and progression in melanoma patients." (PMID 29929490, 2018). "ABCB5 has been shown to be a chemoresistance gene in melanoma and colorectal cancer patients." (PMID 29929490, 2018). "Importantly, ABCB5 is not only a biomarker of melanoma stem cells, but also provides a mechanism for chemoresistance." (PMID 29455657, 2018). "In addition, the changes of ABCB5 differed between the early passages and the late passages of melanoma cells in response to BRAF inhibitor treatment." (PMID 29929490, 2018). "They showed that ABCB5 expressing melanomas had variable gene expression and suggested that the ABCB5 gene may be differentially regulated by individual melanomas." (PMID 29929490, 2018). "The purpose of this study is to determine whether ABCB5 is highly expressed in BRAF inhibitor-resistant melanoma cells and to evaluate whether ABCB5 is involved in the development of resistance to BRAF inhibitors in cutaneous melanoma." (PMID 29929490, 2018). "However, little has been studied regarding the roles of ABCB5 on BRAF inhibitor-resistant melanoma cells." (PMID 29929490, 2018). "The purpose of this study was to clarify whether ABCB5 was involved in PLX resistance in melanoma cells." (PMID 29929490, 2018). "Previously, we reported the expression of ABCB5 in unenriched whole blood from melanoma patients by RT-PCR and showed that ABCB5 transcripts were present in 40% of melanoma cases at all stages, particularly in those with disease recurrence (49%) and metastatic disease (52%)." (PMID 28978038, 2017).